NUF2 (NUF2 component of NDC80 kinetochore complex)
Diseases named in the same sentence as NUF2 in open-access papers (continued):
Sharing a sentence is not in itself a finding about the gene and the disease.
tumor (continued). "In the CDX model of zebrafish, knockdown of NUF2 resulted in more significant tumor suppression in KHM-5M cells than in 8505C cells." (PMID 39242581, 2024). "Silencing NUF2 inhibited proliferation, induced apoptosis of OC cells in vitro and blocked tumor growth in vivo." (PMID 36670423, 2023). "In GBM, NUF2 promoted tumorigenesis and its downregulation inhibited the growth of tumor cells and induced apoptosis." (PMID 36900109, 2023). "The R program analysis showed a correlation of NUF2 with cell proliferation and tumor stemness in the BRCA patient samples." (PMID 36835637, 2023). "In our research, genomics and proteomics data implied that the mRNA and protein abundances of NUF2 were high in the tumor tissues of CCA, and patients with higher NUF2 expression had a poorer prognosis." (PMID 37056930, 2023). "We also showed NUF2 silencing in mice harboring OC xenograft tumors induced a great reduction in tumor size and markedly suppressed levels of Ki-67." (PMID 36670423, 2023). "The spheroid experiment also showed that NUF2 overexpression promotes the proliferative capacity of tumor stem cells." (PMID 36835637, 2023). "As expected, overexpression of TFR1 significantly reversed the tumor inhibitory effect of NUF2 knockdown on cell proliferation and migration, which suggested that TFR1 was involved in NUF2 induced CCA malignancy, at least partly through the regulation of TFR1." (PMID 37056930, 2023). "The experimental results illuminated that the overexpression of NUF2 statistically upregulated the proliferation and tumor stemness ability of the BRCA cell lines MCF-7 and Hs-578T." (PMID 36835637, 2023). "The results, thus, showed that NUF2 was positively correlated with most of the tumor stemness markers." (PMID 36835637, 2023). "The results showed that NUF2 expression was higher in tumor tissues than matched normal bile duct tissues." (PMID 37056930, 2023). "The ratio of lymphatic metastasis, tumor size>5cm, and vascular invasion was significantly higher in NUF2 high expression group than that in low expression group." (PMID 37056930, 2023). "Western blot also showed that the protein level of NUF2 was significantly increased in tumor tissues." (PMID 37056930, 2023). "The relationship between NUF2 expression and the state of tumor-infiltrating immune cells was further investigated on the basis of the expression level of immune markers in ccRCC." (PMID 37138262, 2023). "Upon the Western blot examination of NUF2 overexpression, the expression of the given tumor stemness marker was also stimulated." (PMID 36835637, 2023). "Compared with the PBS (control) and negative control group (si-control), mice in the si-NUF2 injection group (si-NUF2) exhibited slower tumor growth rate (P < 0.05) and lower tumor weight at the endpoint." (PMID 36670423, 2023). "Next, qRT-PCR analysis of NUF2 in 67 pairs of ccRCC and matched tumor-adjacent tissues showed that NUF2 was significantly increased in tumor tissues." (PMID 35813477, 2022). "This was further confirmed by the higher immunoreactive score of NUF2 staining in the tissues of patients with higher tumor grades and advanced TNM stages." (PMID 35813477, 2022). "Since NUF2 levels were correlated with tumor size and poor clinical outcomes, we further investigated the role of NUF2 in ccRCC." (PMID 35813477, 2022). "We studied the effects of NUF2 expression on proliferation, migration, invasion, and tumor growth using LUAD cell lines." (PMID 35814368, 2022). "NUF2 downregulation decreased cell proliferation, migration, invasion and tumor growth in nude mice." (PMID 36620547, 2022). "To further confirm the biological functions of NUF2, we established a xenograft tumor model by inoculating OVCAR3 cells transfected with shNUF2 or shNC and monitored tumor size." (PMID 36620547, 2022). "Meanwhile, the effect of NUF2 downregulation on tumor growth in vivo was determined by xenograft tumor models." (PMID 36620547, 2022).
tumor (continued). "By analyzing the relationship of NUF2 with cell cycle and tumor-related genes, it showed that NUF2 was involved in tumorigenesis and development." (PMID 34178642, 2021). "The relationships between Nuf2 and biomarkers of tumor immune infiltration were analyzed using TIMER and GEPIA." (PMID 33767990, 2021). "Nuf2 expression in tumor cells was examined using the TIMER and Oncomine databases, and its prognostic potential was assessed via the Kaplan-Meier plotter and GEPIA databases." (PMID 33767990, 2021). "In vitro studies confirm the possible role of naked siRNA in suppressing PC progression via down-regulating tumor-promoting genes such as NUF2, Survivin, RAP80, HIF-1α and hTERT." (PMID 34943856, 2021). "In this study, it was found that NDC80, NUF2, SPC24 and SPC25 genes were differentially expressed in tumor tissues and normal tissues and NDC80, NUF2, SPC24 and SPC25genes have diagnostic values for LUAD." (PMID 32226507, 2020). "Moreover, we found that NEK2 and NUF2 were overexpressed in GBC tumor tissues and validated their function in the pro-proliferation of GBC cells." (PMID 40220284, 2025). "Both tumor volume and tumor weight were dramatically attenuated after deletion of NUF2." (PMID 39242581, 2024). "CCK-8 assay presented that knockdown of MNN abolished NUF2-induced promotion of tumor growth." (PMID 39242581, 2024). "In addition, we established orthotopic ATC tumor model in nude mice and found the tumor growth was significantly inhibited by effect of NUF2 knockdown." (PMID 39242581, 2024). "Additionally, high NUF2 expression in the mediastinal lymph nodes of patients with N0 NSCLC is a marker of early tumor recurrence." (PMID 38472943, 2024). "Silencing of NUF2 in HepG2 human HCC cells can dramatically hampered tumor growth in vivo." (PMID 36710413, 2023). "We found that NUF2 expression was significantly upregulated in OC tumor tissues and OC cells, and might function as a critical prognostic indicator for OC patients." (PMID 36670423, 2023). "Xenograft tumor model was used to validate the role of NUF2 in OC progression in vivo." (PMID 36670423, 2023). "The result showed that overexpression of NUF2 promoted the tumor growth." (PMID 37056930, 2023). "qRT-PCR and Western blot were used to determine whether the knockdown of NUF2 reduces the expression of the tumor stemness markers." (PMID 36835637, 2023). "Furthermore, we observed the effect of NUF2 expression on tumor stemness in BRCA cell lines in vivo." (PMID 36835637, 2023). "Furthermore, our results also demonstrated that oncogenic NUF2 functions as a tumor activator in OC progression by interacting with HNRNPA2B1 via the PI3K/AKT/mTOR signaling pathway." (PMID 36670423, 2023). "Importantly, similar to NUF2, higher HMGA2 expression was associated with higher tumor grades, advanced TNM stages, metastases, and poor OS and DFS." (PMID 35813477, 2022). "Collectively, these findings suggested that NUF2 may drive tumor progression and act as an oncogene." (PMID 35814368, 2022). "Additionally, the expression of lncRNA-Gm31932, miR-344d-3-5p, PRC1, NUF2, cycle-related proteins, and Wnt/β-catenin pathway-related proteins in tumor tissues is consistent with the in vivo experiments." (PMID 35393397, 2022). "NUF2 activates tumor growth and inhibits cell apoptosis, but this gene might be liable for pathogenesis of pituitary prolactinoma." (PMID 33709028, 2021). "Additionally, Nuf2 can also function as a potential biomarker in human tumor diagnosis and immunotherapy." (PMID 33767990, 2021). "Our results show that the association of NUF2 expression with the immune cell and its type marker implicate the negative impact of NUF2 in regulating tumor immunology in LUSC and LUAD." (PMID 34178642, 2021). "The relationships between Nuf2 and tumor immune infiltration were analyzed using TIMER." (PMID 33767990, 2021).
tumor (continued). "Our work demonstrated that Nuf2 could be a potential prognostic biomarker and could be related to tumor immune cell infiltration in HCC." (PMID 33767990, 2021). "NUF2, also named CDCA1 as a part of a protein complex associated with the centromeres, is essential for normal centromere microtubule attachment and chromosome instability in tumor cells." (PMID 34260414, 2021). "We used multiple open-source large datasets to identify the potential target genes regulated by CDKN2B-AS1, and also proved in vivo and in vitro that CDKN2B-AS1 affects KIRC tumor growth and metastasis, at least partly through NUF2, which can also serve as an oncogene to promot tumor progression." (PMID 33608495, 2021). "Suppressing the expression of NUF2 inhibits tumor growth and also stimulates cell apoptosis." (PMID 31681566, 2019). "Moreover, our current findings suggest that NUF2 may act as an oncogene by regulating the level of tumor-infiltrating immune cells and the expression of immune checkpoints." (PMID 37138262, 2023). "Therefore, based on a correlation analysis, we predicted that NUF2 might be involved in tumor stemness development and, subsequently, experimentally confirmed that NUF2 can, indeed, promote the expression of tumor stem cell indicators." (PMID 36835637, 2023). "Through gene enrichment and PPI network analysis, we found that NUF2-related pathways, as well as the associated proteins, were enriched and linked mainly to cell proliferation, and through correlation analysis, we ventured to speculate that NUF2 may affect tumor stem cell competence." (PMID 36835637, 2023). "Nuf2 showed a significant positive correlation with various immune cells, indicating that Nuf2-mediated hepatocarcinogenesis might mobilize the activity of these immune cells and make them play an anti-tumor role." (PMID 33767990, 2021). "Circular RNA FOXK2 aggravates PDAC tumor growth and metastasis by affecting PDXK and NUF2 expression through interaction with RNA binding protein YBX1 and hnRNPK." (PMID 38833016, 2024). "Analysis of the GSE159115 database showed that five genes in malignant and stromal cells differed significantly between tumour and normal tissues, but only MXD3, NUF2 and PLK1 in immune cells." (PMID 38546385, 2024). "The present study aimed to investigate the expression of the NUF2 gene in BRCA and its influence on tumor stemness." (PMID 36835637, 2023). "Finally, we also found that in BRCA, NUF2 may be involved in the immune infiltration of the tumor." (PMID 36835637, 2023). "Therefore, we can speculate that NUF2 may promote the development of tumor stemness." (PMID 36835637, 2023). "Western blot showed that the protein level of NUF2 and TFR1 was significantly increased in tumor tissues." (PMID 37056930, 2023). "Regretfully, U0126 could not inhibit the tumor-promoting effect caused by NUF2." (PMID 37056930, 2023). "We demonstrated the consistent upregulation of NUF2 in LUAD and LUSC datasets, patient tumor tissues, and GEO datasets, supporting the muti-omics analysis that its protein level was upregulated in clinical tissues." (PMID 36499051, 2022). "Consistently, NUF2, KIF4A, KIF18B, DLGAP5, and NEK2 were highly overexpressed, whereas LRRK2 was significantly downregulated in the tumor tissues of all datasets." (PMID 36499051, 2022). "These candidates included five upregulated genes—NUF2, KIF4A, KIF18B, NEK2, and DLGAP5—and one downregulated gene—LRRK2—in the tumor tissues of TCGA databases." (PMID 36499051, 2022). "The results showed that the mRNA expression levels of hub genes (PBK, KIF2C, NUF2, KIF20A, RAD51AP1 and DEPDC1) in tumor samples (EAC, ESCC) were significantly higher than in normal samples (P < 0.05)." (PMID 33403046, 2021). "The results indicated that tumor purity significantly and positively correlated with PBK (R= 0.24, P= 1.13e-03), NUF2 (R= 0.267, P= 2.75e-04), RAD51AP1 (R= 0.275, P= 1.83e-04), and DEPDC1 (R= 0.166, P= 2.56e-02) expression." (PMID 33403046, 2021).
tumor (continued). "Among the genes related to prognosis, the expression levels of CCNB1, NQO1, NUF2, and CHEK1 were high in tumor tissues (p < 0.05)." (PMID 33424998, 2020). "In summary, this study suggests that NUF2 may play a key role in the development and progression of BRCA by affecting tumor stemness." (PMID 36835637, 2023). "We investigated the relationship between NUF2 and tumor immune infiltration and the expression of corresponding immune cell markers via the Gene Expression Profiling Interactive Analysis (GEPIA) and Tumor Immune Estimation Resource (TIMER) databases." (PMID 37138262, 2023). "Next, we detected the levels of PRC1 and NUF2 through RT-qPCR, western blotting and Immunohistochemical, and found that the expression of PRC1 and NUF2 in the tumor tissues of the siRNA-Gm31932-174 treated group was significantly reduced, which reconfirmed the results of in vitro experiments." (PMID 35393397, 2022). "In addition, age, tumor size, histological grade, tumor invasion, TNM stage, metastasis, and NUF2 mRNA and protein levels correlated with the patient survival." (PMID 35813477, 2022). "In addition, ChIP-seq data downloaded from GEO datasets showed higher H3K27ac and H3K4me3 enrichment at the NUF2 promoter region in KIRC tissues and tumor tissue-derived primary cells compared with normal renal tissues." (PMID 33608495, 2021). "Thus, our in vitro and in vivo data confirmed that CDKN2B-AS1 is involved in KIRC progression at least partly through the regulation of NUF2, suggesting that the CDKN2B-AS1/NUF2 axis is important for the regulation of KIRC tumor growth and metastasis." (PMID 33608495, 2021). "Due to the lack of research on NUF2 gene amplification, more research need to focus on the manifestations of NUF2 gene amplification in NSCLC, and the relationship between NUF2 gene amplification and NSCLC drug resistance or tumor cell escape growth inhibition." (PMID 34178642, 2021). "Next, we identified candidate herbs and their effective components that may have an inhibitory impact on tumor progression via three hub genes (TOP2A, NUF2, and CCNB2)." (PMID 33946043, 2021). "A previous study demonstrated that circFOKX2 not only interacts with YBX1 and hnRNPK to elevate the expression of the oncogenes NUF2 and PDXK but also functions as a sponge for miR-942 to upregulate the expression of ANK1, GDNF, and PAX6, which contribute to tumor progression in PDAC." (PMID 34419070, 2021). "Furthermore, besides of TILs (Tumor Infiltrating Lymphocytes), MHC molecules, immunoinhibitors and immunostimulators were discovered the relationship with NUF2 expression in LUAD and LUSC through TISIDB." (PMID 34178642, 2021). "The combined detection of NDC80, NUF2, SPC24 and SPC25 may become a new research direction in LUAD diagnosis and a new target for tumor targeted gene therapy." (PMID 32226507, 2020). "The combined detection of NDC80, NUF2, SPC24 and SPC25 may become a new research direction in tumor diagnosis and a new target for tumor targeted gene therapy." (PMID 32226507, 2020). "For instance, CDCA1, also known as NUF2 (NUF2 component of NDC80 kinetochore complex), could inhibit tumor growth and induce apoptosis in HCC through silencing itself." (PMID 33665158, 2020). "HLA-A24(A*24:02) or HLA-A2(A*02:01)-restricted CTL epitopes were identified that induced tumour-reactive CTLs but not autoimmunity; these epitopes were found to correspond to NUF2 protein." (PMID 30364636, 2018). "Thus, it is not unexpected that dysregulation of NUF2 expression and function can promote tumor formation." (PMID 39703688, 2024). "High NUF2 expression in tumor tissue has a negative impact on tumor prognosis." (PMID 38472943, 2024). "Therefore, it is not surprising that the change of NUF2 expression leading to its dysfunction can promote tumor development." (PMID 37056930, 2023).
tumor (continued). "Similarly, although it is not confirmed that NUF2 can promote tumor stemness development, a large number of findings suggest that NUF2 can promote cell proliferation." (PMID 36835637, 2023). "Therefore, it is not surprising that dysregulation of NUF2 expression and function can promote tumor development." (PMID 35813477, 2022). "We therefore hypothesized that Nuf2 might not be involved in the mechanism of tumorigenesis mediated by M2 macrophage, but mainly play the anti-tumor role via M1 macrophages pathway." (PMID 33767990, 2021). "The IHC results indicated that about 67% of the tumor tissues (2 of 3) with low NUF2 expression showed negative or weak HNRNPA2B1 staining and 80% (8 of 10) of those with high NUF2 expression displayed moderate or strong HNRNPA2B1 staining." (PMID 36670423, 2023). "Several studies have revealed the oncogenic role of NUF2, CDCA3, and KIF14 in tumor, but the mechanism has not been elucidated." (PMID 34699322, 2021). "All of the CTAs with the exception of TTK, were significantly correlated with the prostatectomy Gleason score (CEP55; p = 0.0057, NUF2; p = 0.0051, PBK; p = 0.0295, PAGE4; p = 0.0236); however none were correlated with age, preoperative PSA and tumor stage." (PMID 21917134, 2011).
cardiovascular disease (1 paper, 2024). "However, what effect Nuf2 has on cardiovascular disease is still unclear." (PMID 38994368, 2024).
NUF2 also shares sentences with these, for which no sentence is quoted: gastric cancer (5 papers); esophageal cancer (3); esophageal squamous cell carcinoma (2); head and neck squamous cell carcinoma (2); lung squamous cell carcinoma (2); oral cancer (2); acute myeloid leukemia (1); adenocarcinoma (1); anaplastic thyroid cancer (1); biliary tract cancer (1); bladder cancer (1); bone marrow failure (1); cervical cancer (1); cervical squamous cell carcinoma (1); diffuse gastric adenocarcinoma (1); endometrioid adenocarcinoma (1); endothelial dysfunction (1); Fanconi anemia (1); gallbladder cancer (1); gastric adenocarcinoma (1); gastric intestinal type adenocarcinoma (1); lymphoma (1); microcephaly (1); multiple myeloma (1); nasopharyngitis (1); Oral squamous cell carcinoma (1); papillary renal cell carcinoma (1); testicular germ cell tumor (1); urothelial carcinoma (1); uterine corpus endometrial carcinoma (1).